INSR (insulin receptor)
Diseases named in the same sentence as INSR in open-access papers (continued):
Sharing a sentence is not in itself a finding about the gene and the disease.
Insulin resistance (continued). "Peripheral insulin resistance, dysregulation of glucose metabolism, impairment of insulin signaling, and aberrant expression of alternatively spliced insulin receptor (INSR) isoforms contribute to SKM age-related features." (PMID 39594651, 2024). "Insulin resistance, a prominent pathogenic mechanism in T2DM, results from abnormalities in insulin signaling pathways at various levels, including the insulin receptor, insulin receptor substrate phosphorylation, and the postreceptor signaling pathways, leading to inadequate insulin responsiveness." (PMID 39479660, 2024). "Furthermore, MAFLD and T2DM share insulin resistance as a key pathophysiological feature, which diminishes insulin receptor expression in the brain, impairing critical functions like neuronal plasticity and energy metabolism." (PMID 39335505, 2024). "An elevated NLR may activate inflammatory pathways and cascades by activating corresponding receptors and blocking insulin receptor signaling, consequently leading to insulin resistance and T2DM30." (PMID 38890369, 2024). "The influence of maternal insulin resistance caused by INSR mutations on offspring without the mutation has not been described." (PMID 38461278, 2024). "This could partially explain the insulin resistance observed in our obese rats because PPAR-γ promotes the expression of INSR, ISR-1, and GLUT-4." (PMID 38399437, 2024). "This in turn produces a complex array of clinical findings in which specific endophenotypes, such as myotonia, heart block, or insulin resistance, are linked to splicing defects of particular genes, such as CLCN1 (chloride channel), SCN5A (sodium channel), or INSR (insulin receptor)." (PMID 38165038, 2024). "Recurrent pregnancy loss is associated with insulin resistance, however the incidence of pregnancy loss in women with INSR mutations has not been established." (PMID 38461278, 2024). "Hyperinsulinemia-induced insulin resistance may act as a feedback control mechanism that limits the extent of hyperinsulinemia-mediated insulin receptor activation." (PMID 39769002, 2024). "In addition, insulin resistance leads to a situation in which the insulin receptor (IR) is less responsive to insulin, leading to the blockage of this pathway and altered glycogen synthesis in the diabetic liver and kidney." (PMID 39339687, 2024). "Persistent peripheral insulin resistance may lead to dysregulation of brain insulin receptor signaling." (PMID 38379904, 2024). "In the present study, the expression levels of the insulin receptor and the phosphorylation levels of key mediators in its downstream signaling pathway were analyzed in the liver tissue of MP-treated mice to investigate the impact of MPs on insulin resistance." (PMID 38732183, 2024). "Similarly, maternal obesity was associated with widespread hypomethylation of genes within the hypothalamus of offspring together with hypermethylation of the insulin receptor promoter, resulting in insulin resistance." (PMID 39377073, 2024). "The differential efficacy of ILP-Ap04 in STZ versus glucose-induced diabetes models may provide valuable insights into the mechanisms of insulin receptor interaction and insulin resistance." (PMID 38535452, 2024). "This reduction can alter the cell membrane composition, which may disrupt insulin receptor function and signaling pathways, ultimately contributing to insulin resistance." (PMID 39593801, 2024). "It was discovered that OA could improve insulin resistance through the activation of the level of the insulin receptor substrate (IRS-1) and PI3K/Akt." (PMID 38398510, 2024). "Endogenous insulin receptor/insulin-like growth factor-I receptor/Akt may mediate the effects in promoting tumorigenesis and progression in animal models of insulin resistance." (PMID 38388407, 2024).
Insulin resistance (continued). "First, in vivo experiments have shown that glyphosate exposure leads to elevated H2O2 and LPO levels and reduced antioxidant levels, all of which affect membrane integrity and insulin receptor efficacy in the liver, leading to the development of insulin resistance and diabetes." (PMID 39195702, 2024). "Hyperglycemia in female mice with hyperinsulinemia might be attributed to insulin resistance possibly stemming from reduced INSR expression." (PMID 39337631, 2024). "Fetuin-A is thought to contribute to insulin resistance through multiple mechanisms, including impairment of insulin receptor signaling, inhibition of GLUT-4 translocation, and reduction in PPARγ and adiponectin expression, as shown in obese insulin-resistant mice." (PMID 39409124, 2024). "It has been shown that insulin resistance (IR) and activation of the insulin receptor, as well as the insulin-like growth factor 1 (IGF-1) signaling pathways, play pivotal roles in both the initiation and progression of hepatocarcinogenesis in patients with DM." (PMID 38434702, 2024). "We investigated whether enhancing CNS insulin levels or induction of CNS insulin resistance using an inhibitor of the insulin receptor altered the blood-to-brain transport of radioactively labeled insulin in young, healthy mice." (PMID 37076875, 2023). "These led us to hypothesize that inflammation promotes adipocyte P2Y2R upregulation, which leads to insulin resistance by inhibiting the insulin receptor-AKT signaling pathway." (PMID 38141758, 2023). "Moreover, insulin receptor autophosphorylation is dependent on intracellular magnesium concentrations, making magnesium a direct factor in the development of insulin resistance." (PMID 37764713, 2023). "Additionally, ASE activates the insulin receptor pathway, which is closely related to insulin resistance." (PMID 36865944, 2023). "The rare occurrence of diabetes mellitus in ICMP can be explained by an increased level of galectin-3 in the blood, which can interact with the insulin receptor and protein glycation products, promoting their utilization, which prevents the development of insulin resistance." (PMID 37509589, 2023). "In conclusion, these data highlight the importance of EHD2 for the integrity of the plasma membrane milieu, insulin receptor stability, and downstream insulin receptor signaling events, involved in glucose uptake and ultimately underscore its role in insulin resistance and obesity." (PMID 37703099, 2023). "INSR expression diminished significantly upon induction of insulin resistance (p < 0.001)." (PMID 37158952, 2023). "Increased levels of diacylglycerol (DAG), a precursor to triacylglycerol, correlates with insulin resistance, as DAG has been shown to increase PKCepsilon translocation to the plasma membrane, which causes inhibitory phosphorylation in the beta chain of the insulin receptor." (PMID 37242206, 2023). "Rare mutations of the insulin receptor gene and IRS1 protein lead to insulin resistance." (PMID 37560158, 2023). "Importantly they showed acute (with the insulin receptor antagonist S961) or chronic (high fat diet) insulin resistance accelerated the accumulation of senescent beta cells." (PMID 37822597, 2023). "It is tempting for us to speculate that, by binding to the 3′UTR of the HMGA1 mRNA and facilitating the decay of transcript, increased levels of hsa-miR-1225-3p could produce a down-regulation of the insulin receptor expression and insulin resistance." (PMID 37510186, 2023). "PI3K/pAkt activation in the DRG and sciatic nerve of type 2 DM mice was counteracted in response to an intrathecal injection of insulin associated with decreased DRG insulin receptor expression and up-regulation of JNK activity, a mediator of insulin resistance in other tissues." (PMID 36983051, 2023).
Insulin resistance (continued). "Breast cancer patients with diabetes mellitus developed insulin resistance and chronic hyperinsulinemia which might stimulate insulin receptor signaling and induce breast cancer cell proliferation and growth." (PMID 37143985, 2023). "It has been demonstrated that HFD may induce hippocampal insulin resistance by altering the activation of insulin receptor downstream effectors and transcription factors." (PMID 36672155, 2023). "This opinion may be supported by previous findings indicating that chemerin and resistin induce insulin resistance in skeletal-muscle cells at the level of insulin-receptor glucose uptake." (PMID 36830883, 2023). "Moreover, an increase in age can lead to insulin resistance, insulin secretion and insulin receptor abnormalities." (PMID 37076792, 2023). "Inflammation and metabolic disorders are frequently associated with metabolic dysregulation in the liver and muscles because the accumulation of DAG promotes PKC activation while inhibiting insulin receptor activation, resulting in muscle and liver insulin resistance." (PMID 37241737, 2023). "Regarding the central question of how insulin resistance is originated, our results showed that when the inflammation pathways in adipocytes are activated, ceramide signaling enhances a series of feedback loops that inhibit the pathway of insulin receptor." (PMID 37026009, 2023). "Studies have shown that prolonged administration of a high-fat diet may inhibit the insulin receptor signaling pathway and trigger insulin resistance." (PMID 37324274, 2023). "Similarly, the insulin receptor (INSR) gene is of interest since it encodes the tyrosine kinase family, a critical group of receptors whose abnormalities induce insulin resistance." (PMID 37881324, 2023). "In type 2 diabetes, neurons might exhibit “insulin resistance” as reduced transduction downstream of the insulin receptor signaling." (PMID 36983051, 2023). "Another noteworthy finding was the altered expression of the Hmga1 regulon in stressed mutant females, since a genetic lack of HMGA1 protein was reported to adversely affect insulin receptor (INSR) expression in cells and tissues in individuals with insulin resistance and type-2 diabetes." (PMID 37542675, 2023). "The reduction in insulin resistance induced by GLP1-RAs may restore cardiac metabolic flexibility through the improvement of the insulin receptor, increasing glucose uptake and utilization." (PMID 36836121, 2023). "Recent research has shown that EC ADAM17 can cleave the insulin receptor ectodomain, leading to cellular insulin resistance, which could exacerbate insulin resistance, with the initial upregulation of ADAM17 potentially leading to further GSK3β activation." (PMID 37762417, 2023). "Moreover, increased SOCS1 levels in cultured muscle cells and adipocytes can lead to insulin resistance via the inhibition of tyrosine phosphorylation of insulin receptor substrate proteins and subsequent downstream signaling." (PMID 36609306, 2023). "Overall, in this study, we reveal that ZFYVE28 is involved in insulin resistance by promoting phosphorylated insulin receptor degradation, and ZFYVE28 may be a potential therapeutic target to improve insulin sensitivity." (PMID 37884540, 2023). "However, insulin resistance disrupts INSR-mediated tyrosine kinase activities resulting in insufficient activation of the PI3K/Akt signaling cascade upon insulin stimulation." (PMID 37715850, 2023). "This increase may be due to increased insulin resistance in the PCOS group, which is due to decreased insulin binding to its receptor or defective in receptor autophosphorylation due to insulin receptor mutation." (PMID 37034298, 2023). "By increasing insulin receptor phosphorylation, resveratrol may also enhance insulin signaling in animals with insulin resistance in their skeletal muscles and increased protein levels of IRS-1." (PMID 37241737, 2023).
Insulin resistance (continued). "In these individuals, excess fatty acid influx in the skeletal muscle and liver promotes diacylglycerol-induced insulin resistance, impairs insulin signaling via increased insulin receptor serine phosphorylation, and disrupts mitochondrial oxidative phosphorylation." (PMID 37834765, 2023). "Overall, these findings suggest a sex-differential reliance on intact renal tubular InsR signaling which may be translationally important in type 2 diabetes, obesity, or insulin resistance when renal insulin signaling is reduced." (PMID 37175762, 2023). "Insulin receptor numbers also decrease with age and by insulin resistance." (PMID 36834911, 2023). "This activity is enforced at the higher dose of CPF since the increased levels of p-IRS1 Ser 302 phosphorylation, usually part of the physiological feedback mechanism involved in silencing the insulin receptor signaling deregulated, indeed, in insulin resistance." (PMID 37298533, 2023). "Moreover, they found that SOCS1 and SOCS3 inhibit insulin signaling and cause insulin resistance by inhibiting insulin receptor substrate 1 (IRS1) and IRS2 binding to the insulin receptor in cultured L6 myotubes and 3T3L1 adipocytes." (PMID 36609306, 2023). "Here, the authors show that ZFYVE28 is involved in insulin resistance by promoting the degradation of phosphorylated insulin receptor and ZFYVE28 may be a potential therapeutic target to improve insulin sensitivity." (PMID 37884540, 2023). "Notably, oxidative stress, TNF-α, and IL-1β activate the c-Jun NH2-terminal kinase (JNK), generating insulin signaling interruption by modifying the phosphorylation of insulin receptor and insulin receptor substrate-1, provoking insulin resistance." (PMID 36976988, 2023). "In T2DM, insulin resistance arises due to decreased expression levels of insulin resistance, the altered phosphorylation status of insulin receptor substrate proteins, and impaired activation of axonal growth-related pathways, so providing insulin also fails to alter DPN." (PMID 38264279, 2023). "Furthermore, overexpression of Grb10 inhibits the interaction of the insulin receptor with PI3K, thus reducing insulin signaling and causing insulin resistance." (PMID 36982168, 2023). "In an experimental study in gene-modified mice it was shown that Gal-3 can bind directly to the insulin receptor and inhibit downstream insulin receptor signaling, contributing to decreased insulin signaling and insulin resistance and, at the same time, promote adipose tissue inflammation." (PMID 35277168, 2022). "T cell function was also shown to depend on insulin receptor signaling, which might explain the observed confounding effect by the insulin resistance index HOMA-IR." (PMID 36246898, 2022). "We described that miR-7, which is itself regulated by insulin, impairs insulin signaling and could lead to insulin resistance in the brain through the post-transcriptional regulation INSR, IRS-2." (PMID 36010613, 2022). "Abnormal insulin signals are the basis of insulin resistance, including insulin receptor degradation, excessive activation of protein tyrosine phosphatase, inflammation, and excessive stress-activated IKKbeta, JNK, ERK, S6K, and mTOR kinase, thereby inhibiting phosphorylation of IRS." (PMID 35224109, 2022). "Furthermore, oxidative stress can lead to insulin resistance by disturbing the insulin receptor signaling pathway." (PMID 35418873, 2022). "Taken together, our results indicate that in parallel with the degeneration of rod photoreceptors, the terminals of their post-synaptic horizontal cell partners undergo a putative process of insulin resistance, as evidenced by the decreases in INSR levels and pS6Ser240/244 signaling." (PMID 35444190, 2022). "Insulin receptor defective function may contribute to insulin resistance, including abnormalities in receptor structure, number, binding affinity, and signaling capacity." (PMID 35455055, 2022).
Insulin resistance (continued). "Insulin resistance in this group of patients results from defects at the molecular level, including impaired insulin receptor-related signaling pathways enhanced by obesity and its features: Excess visceral fat, chronic inflammation, and reactive oxygen species." (PMID 35457152, 2022). "The decrease of inflammatory factors could further enhance insulin receptor sensitivity and improve insulin resistance." (PMID 36248820, 2022). "This inhibitory serine phosphorylation event leads to detachment of IRS1 from insulin receptor and consequently to impairments in insulin-mediated signaling that may also lead to insulin resistance." (PMID 36012331, 2022). "Insulin resistance is thought to play a key role in modulating immune cell responses since immune cells that lack the insulin receptor have been shown to have an impaired cytokine secretion and lower antigen presentation activity upon influenza infection in a rodent model." (PMID 35187037, 2022). "Since insulin levels were elevated at puberty, and insulin receptor signaling is necessary for β cell compensation to insulin resistance, we asked whether insulin might mediate the increase in β cell proliferation in response to pubertal serum." (PMID 36107617, 2022). "A puzzling problem might be the coexistence of insulin resistance/hyperinsulinemia with reduced insulin receptor density in brain structures (by up to 80% in severe AD)." (PMID 35565839, 2022). "Stressful events, including sepsis, might trigger hyperglycemia by increasing the secretion of pro-inflammatory mediators, which lead to insulin resistance, as well as altered insulin receptor signaling." (PMID 36143971, 2022). "Elevated IL-6 release might contribute to diabetes progression, as an in vitro study reported the induction of cellular insulin resistance of hepatocytes by IL-6-triggered impairment of insulin receptor signal transduction." (PMID 35163309, 2022). "Furthermore, TNF‐α‐mediated inflammatory signalling pathways impair insulin receptor signal transduction, resulting in insulin resistance, which is crucial for NAFLD progression." (PMID 35713152, 2022). "It is known that TNFα directly impairs insulin signaling through inhibition of tyrosine kinase activity of the insulin receptor and thus could be a critical mechanism whereby adiposity induces peripheral insulin resistance." (PMID 36364884, 2022). "Either excessive or insufficient surface INSR can lead to the development of insulin resistance." (PMID 35165256, 2022). "Furthermore, it worsens insulin resistance by affecting the insulin receptor in the muscle and liver." (PMID 36246911, 2022). "In addition, livers of CKO mice showed attenuated insulin-receptor signaling, demonstrating the critical role of catalase as a connecting element between redox homeostasis, liver lipid handling and insulin resistance in vivo." (PMID 35740032, 2022). "ANGPTL7 was found to play a critical role in inducing insulin resistance, which occurred through multiple mechanisms involving the down regulation of Insulin receptor (INSR), upregulation of suppressor of cytokine signaling 3 protein (SOCS3) to degrade insulin receptor substrate 1 (IRS1)." (PMID 36017324, 2022). "Support for this possibility comes from mice with hepatocyte-specific deletion of the insulin receptor showing that the key consequence of hepatic insulin resistance is deleterious cellular and molecular changes which exacerbate hepatocyte triglyceride storage." (PMID 35734881, 2022). "Our focus on CEACAM1 phosphorylation by the insulin receptor and its role in insulin clearance has provided a mechanistic underpinning for how reduced insulin clearance can cause insulin resistance and is not just a consequence thereof." (PMID 36009446, 2022). "In addition, pigs with elevation blood level of selenium showed downregulation of INSR (insulin receptor) and upregulation of mTOR-s6, regarded as insulin resistance." (PMID 35975984, 2022).